NLRP3 (NLR family pyrin domain containing 3)
Diseases named in the same sentence as NLRP3 in open-access papers (continued):
Sharing a sentence is not in itself a finding about the gene and the disease.
colitis (continued). "Another study demonstrated that NLRP3 inflammasome components act as a protective role in an animal model of acute colitis, in which NLRP3 deficiency enhanced chemically induced colitis-associated CRC occurrence." (PMID 39062587, 2024). "IL-18 secretion by the NLRP3 inflammasome can indirectly reduce tumor progression in colitis-associated colorectal cancer by inducing regulatory T (Treg) cells to produce IFN-γ and enhancing T-cell and NK-cell cytotoxicity." (PMID 39456655, 2024). "Studies also find that compared to wild-type mice, mice with NLRP3 inflammasome deficiency exhibit exacerbated DSS-induced colitis and decreased epithelial integrity." (PMID 38455052, 2024). "Among them, the NLRP3 pathway has been shown to activate GSDMD in a mouse model of colitis-associated colon cancer and mediate the release of IL-1β and IL-18." (PMID 38898209, 2024). "Administration of YU102 in the DSS-treated colitis model mice caused suppression of the NLRP3 protein levels and accompanied inflammatory cytokine release in the intestinal epithelium." (PMID 38667290, 2024). "Taken together, these results highlight that the protective effect of ruscogenin on DSS-induced colitis was associated with the attenuation of NLRP3 inflammasome activation and caspase-1-dependent pyroptosis by inhibiting the TLR4/NF-κB pathway." (PMID 38790951, 2024). "Conversely, Nlrp3(-/-) mice displayed heightened susceptibility to experimental colitis, underscoring its vital role in maintaining intestinal homeostasis." (PMID 38482005, 2024). "Considered together, these data suggest that CSCC-induced inhibition in colitis is closely associated with the suppression of the STAT3/NLRP3 signaling pathway." (PMID 39329121, 2024). "In IL-10-deficient mice, Glyburide suppressed NLRP3 inflammasome activation, acting both preventively and by improving ongoing colitis." (PMID 39684769, 2024). "Pretreatment with E. faecalis or NLRP3 siRNA has been shown to inhibit NLRP3 inflammasome activation in macrophages and slow the progression of colorectal tumors associated with colitis in mice." (PMID 38892354, 2024). "In CRC mice models, the protective role of the NLRP3 inflammasome was shown, and its deficiency made the mice more susceptible to colitis and colitis-associated colorectal cancer induced by AOM/DSS." (PMID 39684769, 2024). "Although activated caspase-1 is crucial for DSS-induced inflammation, caspase-1- or NLRP3-deficient mice developed significantly less severe colitis than wild-type mice." (PMID 37240022, 2023). "These outcomes show the post- and pre- Treatment effect of a polyphenolic extract rich in anthocyanins from maqui the acute phase of TNBS- induced CD-like colitis is linked to suppression of the NLRP3 inflammasome and reduced MC responses." (PMID 38283356, 2023). "Mechanistically, ECE exhibited protective effects against pathogenic colitis by inhibiting the NLRP3/NF-κB pathways known to be pivotal regulators in the inflammatory signaling cascade." (PMID 38138587, 2023). "NR4A1 inhabits pyroptosis by transcriptionally inhibiting NLRP3 and IL-1β and colocalizing with NLRP3 in trans-Golgi to alleviate pathogenic bacteria-induced colitis." (PMID 37238692, 2023). "In the last decade, inverse associations between miR-223 and NLRP3 were reported in multiple tissues and cells, including colons of miR-223−/y mice with colitis induced by dextran sulfate sodium (DSS), lung macrophages, and livers of miR-223−/− mice." (PMID 37710276, 2023). "This study found that TFGU suppressed the activation of the NLRP3 inflammasome in mice with colitis caused by irinotecan." (PMID 37849728, 2023). "The NLRP3 inflammasome is important for maintaining a balanced in the gastrointestinal tract since Nlrp3-/- mice displayed a unique intestinal microbiota and are more susceptible to experimental colitis." (PMID 36761775, 2023).
colitis (continued). "Here, we studied the role of endogenous IL-38 in a murine model of DSS colitis by comparing responses in WT to those in IL-38 deficient mice, focusing particularly on the involvement of the NLRP3 signaling." (PMID 35693797, 2022). "This is evident for the best characterized NLRP3-containing inflammasome, whereby mice deficient in NLRP3 are more susceptible to azoxymethane/dextran sodium sulfate (AOM/DSS)-induced colitis-associated colon cancer (CAC)." (PMID 35299732, 2022). "Studies also found the deficiency of NLRP3 inflammasome composition increases susceptibility to experimental colitis in mice." (PMID 36389791, 2022). "NLRP3 deficient mice are susceptible to DSS-induced colitis induction and NLRP3−/− mice are prone to develop more severe colitis compared to controls responding to C. rodentium infection." (PMID 35320937, 2022). "Induction of autophagy by certain small molecular agents were reported to protect against colitis-associated colorectal cancer via suppressing the NLR family pyrin domain containing 3 (NLRP3) inflammasome activation." (PMID 36091106, 2022). "Research on the NLRP3 inflammasome in colorectal tumors is mainly focused on its function in colitis-associated CRC, and it is controversial." (PMID 36619871, 2022). "Collectively, these observations serve as a proof-of-concept for designing host-oriented therapeutic strategies and further demonstrate an engineered eNAMPT-induced NLRP3 inflammasome network associated with colitis." (PMID 36552583, 2022). "The researchers showed that CA was effective in preventing DSS induced colitis associated conditions, it prevented activation of the NLRP3 inflammasome and production of pro-inflammatory cytokines in the colon." (PMID 36090968, 2022). "The IL-38 deficiency that aggravated DSS colitis was associated with elevated gene expression and protein levels of NLRP3 inflammasome and enhanced IL-1β signaling at the time of sacrifice." (PMID 35693797, 2022). "IL-18 is a proinflammatory interleukin matured by NLRP3 inflammasome activation, and IL-18 equilibrium in the epithelium has been implicated in barrier function in colitis, where IL-18 coordinates goblet cell maturation transcriptional programs." (PMID 36145301, 2022). "Concordantly, loss of Nlrp3, Asc or caspase-1 led to severe colitis but also to colitis-associated CRC (CAC)." (PMID 35517498, 2022). "Reports are suggesting that IL-1β and IL-18 induced by the NLRP3 inflammasome confer protection against colitis and colitis-associated tumorigenesis." (PMID 36389791, 2022). "Other research conducted in 2019 on C57 BL/6 mice that were injected with azoxymethane intraperitoneally, showed that inhibiting NLRP3 protected against tumorigenesis in colitis-associated CRC." (PMID 35877745, 2022). "Our data suggest that during the recovery from colitis, IL-38 deficient animals have detrimental NLRP3 activity, and NLRP3 inhibition attenuates the recovery process." (PMID 35693797, 2022). "Atractylenolide I inhibits NLRP3 inflammasome activation in colitis-associated colorectal cancer via suppressing Drp1-mediated mitochondrial fission." (PMID 34335248, 2021). "The NLRP3 activation by P. mirabilis is critical for the exacerbation of colitis caused by the colonization of this bacterium." (PMID 34705319, 2021). "The mechanism of EA to attenuate colitis is associated with the inactivation of the NLRP3/IL-1β pathway and improvement of the Nrf2/HO-1 pathway." (PMID 35095910, 2021). "Accumulative evidence suggests that the activation of NLRP3 inflammasomes and pyroptosis are associated with the inflammatory process of colitis." (PMID 34628369, 2021). "Nlrp3- and Caspase 1-deficient mice were reported to show ameliorated colitis severity, while others reported that DSS-induced colitis was aggravated in these mice." (PMID 34721422, 2021).
colitis (continued). "In contrast, an autoimmunity-associated PTPN22 variant (V619W) that leads to increased PTPN22 function causes increased NLRP3 inflammasome activation and excess IL-1β production that protects mice from experimental colitis." (PMID 33808793, 2021). "As colitis is associated with activation of the NLRP3 inflammasome, we used ATP- or DSS-activated macrophages to examine the interaction between Rubicon and p22phox in vitro." (PMID 34943057, 2021). "In contrast, other studies have found that mice with NLRP3, ASC, or caspase-1 deficiency exhibited more severe experimental colitis and decreased intestinal epithelial integrity, suggesting a protective role of the NLRP3 inflammasome." (PMID 34322027, 2021). "The research of NLRP3 inflammasome in the occurrence and development of colorectal tumors mainly focuses on its mechanism in colitis-associated colorectal cancer." (PMID 34955826, 2021). "NLRP3 has been proved to be associated with A. muciniphila abundance in colitis in both mice and humans." (PMID 34612661, 2021). "In colitis animal models, the NLRP3 inflammasome has been regarded to have both pathogenic and protective effects." (PMID 34322027, 2021). "Using the DSS-colitis model, they found that mice bearing NLRP3-R779C mutation in hematopoietic cells showed intensified colitis, which was ameliorated by downregulation of BRCC3 or JOSD2." (PMID 33808793, 2021). "Further evidence indicated that AhR is an inhibitor of NLRP3 inflammasome in bowel inflammation and colitis-associated colorectal cancer." (PMID 34868022, 2021). "A recent study showed that PAFR regulates lung inflammation caused by colitis through NLRP3 signaling." (PMID 34104104, 2021). "Because NLRP3 inflammasome protects against loss of epithelial integrity and mortality during experimental colitis." (PMID 32950971, 2020). "For example, VSIG4 was found to exacerbate an experimental model of colitis in which NLRP3 inflammasome activation is associated with limiting disease progression." (PMID 32856419, 2020). "Both loss of NLRP3 as well as PTPN22 resulted in aggravation of acute DSS colitis, while presence of the R619W variant protected the animals from developing intestinal inflammation." (PMID 32751912, 2020). "The NOD-, LRR- and pyrin domain-containing protein 3 (NLRP3) inflammasome has been extensively studied in part due to its strong association with colitis and CAC." (PMID 32456012, 2020). "And we found that NLRP3 deficiency aggravates DSS-induced colitis by exacerbating gut structure and tight junction (Occludin)." (PMID 32950971, 2020). "Polymorphism in the NLRP3 gene is linked to colitis severity and progression in patients, and gain-of-function mutations in the NLRP3 gene that increase the production and secretion of IL-1β and IL-18." (PMID 32545788, 2020). "Pyroptosis and NLRP3 inflammasome are associated with various kinds of inflammatory diseases including colitis." (PMID 32950971, 2020). "Oral administration of DSS to NLRP3-deficient mice was reported to have resulted in a loss of epithelial integrity, systemic dispersal of the microbiota, and more severe colitis." (PMID 33143375, 2020). "Small molecules, including GL-V9 (AMPK activator), exhibited strong anti-inflammatory effects by activating autophagy and inducing NLRP3 degradation, preventing colitis-associated colorectal cancer through." (PMID 32703253, 2020). "iUVRAGFS mice display increased inflammatory response in sepsis, intestinal colitis, and colitis-associated cancer development through NLRP3-inflammasome hyperactivation." (PMID 31831743, 2019). "MiR-223−/− mice exhibit exacerbated DSS-induced colitis and an increased level of IL-1β through the loss of repressive function on NLRP3 targeted by miR-223-3p." (PMID 30755244, 2019).
colitis (continued). "Nowadays, the majority of available studies have investigated the role of NLRP3 in several experimental models of colitis, highlighting remarkable beneficial effects associated with the pharmacological modulation of this enzymatic complex." (PMID 30559669, 2018). "Increasing evidences suggest that NLRP3 inflammasome is associated with chronic colitis and colitis-induced colon cancer." (PMID 28938606, 2017). "Independent research groups confirmed that Nlrp3-deficient mice were more susceptible to DSS-induced colitis and relevant symptoms like weigh loss were more severe." (PMID 28360909, 2017). "In contrast, mice deficient for NLRP3 were less sensitive to DSS-induced acute colitis, and TER treatment exerted little protective effect on DSS-induced intestinal inflammation in NLRP3−/− mice." (PMID 28553294, 2017). "The mechanisms underlying the inhibitory effects of MALT1 in DSS-induced colitis have been ascribed to the inhibition on NF-κB and NLRP3 inflammasome activation in macrophages, thus implying that MALT1-NF-κB signaling regulates NLRP3 inflammasome activation." (PMID 28179906, 2017). "Increasing evidence imply that activation of NLRP3 inflammasome is involved in DSS-induced colitis, which characterized by weight loss, bloody faeces and inflammation, although the precise mechanisms remains controversial." (PMID 28978034, 2017). "Nevertheless, NLRP3 inflammasome was demonstrated as a negative regulator of tumorigenesis in colitis-associated and liver cancers." (PMID 28865486, 2017). "In this study, we investigated the anti-inflammatory effect of Huaier in dextran sulfate sodium (DSS)-induced murine colitis and revealed the underlying mechanisms by targeting NLRP3 inflammasomes." (PMID 28380426, 2017). "Several lines of evidence point out the concept that deficiencies in NLRP3 inflammasome components can protect mice from DSS-induced colitis." (PMID 28179906, 2017). "In murine models, PTPN22 deficiency results in pronounced colitis, increased NLRP3 phosphorylation, but reduced levels of mature IL-1β." (PMID 28561062, 2017). "Compared with WT mice, deletion of NLRP3 significantly attenuated the severity of symptoms in DSS-induced colitis, with decreased weight loss, colon shortening and spleen enlargement." (PMID 28938606, 2017). "To further assess the role of IL-15 in the increased susceptibility of Nlrp3−/− to DSS-induced colitis, we employed an antibody-based neutralization strategy." (PMID 27610005, 2016). "We reported previously that Nlrp3−/− mice were more susceptible to colitis and exhibited reduced colonic IL-10 expression." (PMID 27610005, 2016). "In a previous study, we reported that Nlrp3−/− mice were more susceptible in experimental models of colitis, exhibiting decreased intestinal barrier function, altered expression of antimicrobial peptides, and a unique intestinal microbiota." (PMID 27610005, 2016). "NLRP3−/− mice with colitis exhibited significantly greater weight loss than WT mice on days 1 and 2, and non-significantly greater weight loss than WT mice on day 3 (p = 0.053)." (PMID 27966619, 2016). "There is similar controversy regarding the role of the inflammasome in mouse models of IBD, with some studies demonstrating that deficiency of NLRP3 or caspase 1 reduced the severity of colitis while others showed the opposite effect." (PMID 27505062, 2016). "It has been reported that the polymorphism in the Nlrp3 gene is closely associated with the colitis severity and progression in patients with IBD." (PMID 28119697, 2016). "Lastly, inhibition of IL-15 signaling with a neutralizing antibody protected Nlrp3−/− from colitis, an effect that was associated with a reduction in the expression of IL-17 in colonic tissue." (PMID 27610005, 2016). "In vivo, HU308 treatment attenuated DSS-induced colitis mice associated with reduced colon inflammation and inhibited NLRP3 inflammasome activation in wild-type mice." (PMID 27611972, 2016).
colitis (continued). "NLRP3-deficient mice have also been shown to be more susceptible to DSS-induced colitis, to have a dysbiotic microbiota, and to present altered colonic β-defensin expression and decreased antimicrobial capacity." (PMID 26925061, 2016). "Enhanced susceptibility to chemical-induced colitis has also been demonstrated for the NLRP3 inflammasome." (PMID 25879288, 2015). "Primary peritoneal macrophages, the DSS mice model, and Nlrp3-deficient mice, were used to assess the effect apoptotic cells on colitis." (PMID 25822487, 2015). "In the DSS colitis model and DSS-AOM colitis associated colon cancer murine models, several inflammasomes including NLRP3, NLRP6 and NLRC4 have been found to protect against dysplasia and hyperplasia in the colon." (PMID 26378020, 2015). "Specifically, both NLRP6 and NLRP3 deficiencies are linked to exacerbation of chemical-induced colitis." (PMID 25879288, 2015). "Studies in macrophages and mouse models of colitis have linked abnormal NLRP3 inflammasome activation with inflammatory bowel disease, including ulcerative colitis and Crohn’s disease." (PMID 26594174, 2015). "They further show that NLRP3-deficient mice are protected from DSS-induced colitis, exhibiting a significantly reduced production of pro-inflammatory cytokines as well as improved clinical assessments and histological scores." (PMID 26484345, 2015). "In a colitis-associated colon cancer model, NLRP3 inflammasome works through myeloid cells whereas NLRC4 inflammasome plays a role in epithelial cells." (PMID 24474192, 2014). "NLRP3-deficient mice had been reported to show increased susceptibility to dextran-sulfate-sodium- (DSS-) induced colitis with increased mortality and weight loss in three different studies." (PMID 23843683, 2013). "In particular, leucine-rich-repeat-containing Nlrp3−/− mice show an increase in acute and recurring colitis and colitis-associated cancer, although the disease outcome is less severe in Nlrp3−/− mice than in Pycard−/− or Casp1−/− animals." (PMID 23847622, 2013). "Mechanistic insights from previous studies have also highlighted impaired production of type I and III interferons in XLA patients following enteroviral infections, as well as dysregulated IL-1β signaling and NLRP3 inflammasome hyperactivation in BTK-deficient colitis models." (PMID 40963632, 2025). "This implies that NLRP3 expression increases the susceptibility to colitis." (PMID 40534879, 2025). "Further studies reveal that the toll-like receptor 2/4 (TLR2/4)-NF-κB-NOD-like receptor thermal protein domain associated protein 3 (NLRP3) axis exacerbates colitis by inducing macrophage pyroptosis and IL-1β secretion, amplifying intestinal inflammation and barrier dysfunction." (PMID 41030455, 2025). "Moreover, NLRP3 inhibitor MCC950 effectively reversed the exacerbation of colitis triggered by Vangl2 deficiency." (PMID 39899477, 2025). "Finally, NLRP3-deficient mice were reported to be susceptible to colitis, and this condition was, at least in part, determined by increased epithelial barrier damage." (PMID 40227443, 2025). "It regulates the NLRP3-mediated inflammatory signaling pathway negatively, inhibits the secretion of proinflammatory mediators and activation of macrophages, reduces the intestinal inflammation level and limits the development of colitis-associated cancers." (PMID 41357232, 2025). "In an animal study of colitis, the use of 2-bromopalmitate (2-BP), a palmitoylation inhibitor, improved survival rates and reduced weight loss, indicating that regulating NLRP3 palmitoylation is a prospective therapeutic strategy for NLRP3-driven inflammatory diseases." (PMID 40681504, 2025). "Previous studies have shown that NLRP3 deficiency is associated with a significantly increased incidence of colitis and colorectal cancer induced by the DNA-damaging agent azomethane (AOM) and the chemical colitogenic dextran sulfate sodium (DSS) in mouse models." (PMID 39325798, 2024).